WRN (WRN RecQ like helicase)
Diseases named in the same sentence as WRN in open-access papers (continued):
Sharing a sentence is not in itself a finding about the gene and the disease.
colorectal cancer (21 papers, 2008 to 2025). A primary or metastatic malignant neoplasm that affects the colon or rectum. "Our investigation, which demonstrates the association between impaired removal of TOP1cc and defective NF‐κB activation and WRN deficiency, explains enhanced survival of colorectal cancer patients with WRN deficiency in response TOP1 inhibitor treatment." (PMID 35582959, 2022). "Although infrequent, WRN defects are associated with gastric cancer roughly 25% of the time, while it is considered a top ranked gene associated with advanced colorectal cancer." (PMID 25018888, 2014). "Others have examined specific aspects of WRN expression in colorectal cancer, such as the presence of allelic variants and colorectal cancer risk and WRN promoter methylation as it correlates with a CpG island methylation phenotype (CIMP)-high diagnosis." (PMID 22682314, 2012). "Indeed, in colorectal cancer, one study demonstrated that epigenetic silencing of WRN was associated with improved survival in patients treated with a topoisomerase inhibitor, while another study was not able to validate these findings." (PMID 35782872, 2022). "Although WRN has been introduced as a candidate gene for hereditary breast cancer, the inheritance of the variant from the maternal side has sparked a debate on its role in developing colorectal cancer." (PMID 34164337, 2021). "An example of this includes genome-wide CRISPR knockout screens in MSI colorectal cancers that pinpointed the WRN helicase as a synthetic-lethal vulnerability, prompting the preclinical development of WRN inhibitors." (PMID 41463180, 2025). "VVD-133214 is a newly discovered small molecule that allosterically modifies WRN Cys727, hindering necessary interdomain interactions for WRN helicase activity and causing synthetic lethality in MSI-high colorectal cancer cells." (PMID 40196015, 2025). "Immunofluorescence microscopy revealed significantly higher WRN expression in the crypts of colorectal cancer regions compared to adjacent normal tissues." (PMID 40261911, 2025). "Recent studies have shown that WRN expression is upregulated in cultured colonic and gastric cancer cell lines, promoting survival in colorectal cancers." (PMID 40261911, 2025). "Survival of colorectal cancer patients with low expression of WRN was significantly increased after TOP1 inhibitor treatment." (PMID 35582959, 2022). "One study investigated polymorphisms in WRN, RMI1, and BLM in a large population-based case-control study of colorectal cancer patients and controls and found an association of BLM P868L with rectal cancer risk." (PMID 35782872, 2022). "With respect to colorectal cancer, hypermethylation of the WRN promoter is commonly found, reducing its expression." (PMID 25018888, 2014). "With the PMS2 and WRN results, a pathological connection can be found between the patient's jejunal cancer and colorectal cancer." (PMID 25018888, 2014). "WRN hypermethylation in epithelial tumors was most prevalent in colorectal cancer (37.9%, 69/182), followed by non-small cell lung (37.5%, 21 /56), gastric (25%, 10/38), prostate (20%, 4/20), breast (17.2%, 10/58), and thyroid (12.5%, 4/32) tumors." (PMID 24359226, 2013). "Germline variants of WRN were described in HBOC and early-onset familial colorectal cancer." (PMID 37628631, 2023). "Indeed, the BRAF mutant colorectal cancer cell lines that show vulnerability to WRN knock-down are all MSI high, suggesting that this is the underlying molecular defect directly responsible, rather than BRAF mutations." (PMID 36295658, 2022). "WRN methylation is a sensitive marker for prediction of irinotecan in colorectal cancer." (PMID 32974031, 2020). "We assessed this study to investigate the molecular profile of WRN-mut in colorectal cancer (CRC)." (PMID 32455893, 2020). "Primary tumors of colorectal cancer patients and cell lines display decreased WRN mRNA and protein expression; however, no WRN mutations have been associated with colorectal cancer risk." (PMID 29043077, 2017).
colorectal cancer (continued). "Besides, WRN hypermethylation in colorectal tumors is a predictor of good clinical response to irinotecan, which is commonly used in the treatment in colorectal cancer." (PMID 24359226, 2013). "RECQL1, WRN, and RECQL5 mRNA expression have been found to be lower in primary colorectal carcinoma (CRC) samples compared to normal colonic mucosa, while BLM and RECQL4 mRNA levels are increased." (PMID 35782872, 2022). "A new investigation has discovered a hopeful synthetic lethal connection between disabling/restraining the WRN DNA helicase and colorectal cancer with MSI, a characteristic that emerges due to a lack of DNA mismatch repair." (PMID 37626815, 2023). "Further, to evaluate whether the role of WRN is U2‐OS cell line specific, HCT116 colorectal cancer cells were also employed." (PMID 35582959, 2022).
progeroid syndrome (21 papers, 2011 to 2025). A group of rare genetic disorders which mimic physiological aging, making affected individuals appear to be older than they are. "Despite the link between WRN deficiencies and progeria, our analyses of human colon tissues, mouse crypts, and Drosophila midguts revealed that WRN expression does not decrease but rather increases in intestinal stem cells (ISCs) with aging." (PMID 40261911, 2025). "LMNA mutations are the second most common genetic cause of progeroid syndromes after WRN mutations in our Registry." (PMID 32954377, 2020). "On the other hand, mutations in the WRN helicase causing a segmental progeroid syndrome have been associated with an elevated cancer risk." (PMID 29635765, 2018). "Another commonly seen progeroid syndrome is WS, caused by mutations in WRN gene that encodes a RecQ DNA helicase important to DNA replication and DNA damage repair." (PMID 29476423, 2018). "The most intriguing examples are LMNA and WRN: while specific variants of these two genes determine progeria and accelerated aging, alternative variants may increase life span." (PMID 22279548, 2012). "Despite extensive studies of the link between WRN and progeria phenotypes, its physiological function in natural aging remains largely unexplored." (PMID 40261911, 2025). "The Werner (WRN) gene codes for a DNA helicase that contributes to genomic stability and has been identified as the gene responsible for progeria." (PMID 22797812, 2012). "Therefore, LMNA mutation and WRN deficiency does not facilitate EC senescence, suggesting that the premature aging caused by progeria-associated mutations are cell-type-specific." (PMID 29476423, 2018).
Rothmund-Thomson syndrome (16 papers, 2007 to 2025). "Of the five human RecQ families, three are genetically linked to cancer syndromes and premature diseases, such as Bloom’s syndrome (BLM gene mutations), Werner’s syndrome (WRN gene mutations), Rothmund-Thomson syndrome (RTS), RAPADILINO, and Baller-Gerold syndrome (caused by mutation of RECQ4)." (PMID 34381789, 2021). "For example, deficiencies in RecQ family helicases BLM/RECQ2, WRN/RECQ3, and RTS/RECQ4 lead to Bloom, Werner, and Rothmund-Thomson syndromes, respectively." (PMID 34912850, 2021). "Sgs1 is a RecQ family DNA helicase and a homolog of the human BLM, WRN, and RECQL4 proteins that are mutated in Bloom's, Werner, and Rothmund Thomson syndromes, respectively." (PMID 23271978, 2012). "Loss of function of three of these results in cancer predisposition disorders Bloom's syndrome (BS, defective in BLM), Werner's syndrome (WS, defective in WRN) and Rothmund Thomson syndrome (RTS, defective in RECQ4)." (PMID 20808892, 2010). "Although no hereditary disease has been linked with the RECQL gene to date, mutations in three of five RecQ genes, BLM, WRN and RECQ4, lead to Bloom, Werner, and Rothmund-Thomson syndromes, respectively, and are associated with cancer predisposition and/or premature aging." (PMID 25945795, 2015). "Also, Mutations in the helicases, including Bloom syndrome protein (BLM), Werner syndrome protein (WRN) and ATP-dependent DNA helicase QL4 (RecQL4) that mediate replication fork remodeling and restart can result in the development of Bloom, Werner and Rothmund-Thomson syndromes, respectively." (PMID 31717862, 2019).
osteosarcoma (12 papers, 2014 to 2024). A usually aggressive malignant bone-forming mesenchymal neoplasm, predominantly affecting adolescents and young adults. "Imperatively, WRN‐deficient osteosarcoma, melanoma, and colon carcinoma were highly sensitive to nanomolar concentration of CPT." (PMID 35582959, 2022). "Previously, we have shown that WRN expression protects osteosarcoma cells from the toxic effects of the TOP1ccs at micromolar concentration of CPT." (PMID 35582959, 2022). "In order to evaluate the role of WRN in cancer resistance to TOP1cc, WRN expression was abolished in U2‐OS osteosarcoma by CRISPR‐Cas9 double nickase system (WRN‐KO vs. WRN‐WT cells expressing control CRISPR‐Cas9 double nickase vector)." (PMID 35582959, 2022). "In another study, they utilized WRN knockdown osteosarcoma cells and 50 % of cells died after exposure to 10 μM of etoposide." (PMID 24429382, 2014). "However, one study conducted using ALT-positive U20S osteosarcoma cells demonstrated a function for WRN in T-oligo–induced responses." (PMID 28218725, 2017). "One study performed with the U20S osteosarcoma cell line, which is ALT-positive, examined the involvement of Werner syndrome helicase (WRN) in T-oligo-induced responses in these cells." (PMID 30189661, 2018).
melanoma (11 papers, 2013 to 2024). A malignant, usually aggressive tumor composed of atypical, neoplastic melanocytes. "In correlation with patient data and above results, the TOP1 inhibitor‐based targeted therapy showed that WRN‐deficient melanoma tumors were highly sensitive to TOP1 inhibition in preclinical in vivo mouse model." (PMID 35582959, 2022). "Altogether, 7/11 double mutation carriers (excluded from the analysis of clinicopathological data) carried at least one mutation in high-risk melanoma (POT1/CHEK2) or syndromic (ATM/WRN, BRCA1, BRCA2 (2x), CHEK2/RAD51D, NBN) genes." (PMID 33050356, 2020). "Geographic differences in thyroid neoplasms and melanomas cannot be explained by differences in the frequency of specific WRN mutant alleles, as many of the same pathogenic mutations have been found in WS patients residing in Japan or elsewhere." (PMID 23573208, 2013). "Finally, we assessed therapeutic potential of TOP1 inhibitor for targeting WRN‐deficient melanoma tumor, which otherwise is known to be resistant to other therapeutic modalities." (PMID 35582959, 2022). "The germline variants of BRCA2, POLE, WRN, FANCI, PALB2, and RAD54B genes, involved in DNS repair mechanisms, have been implicated in rendering melanoma patients more susceptible to tumor progression and affecting their response to treatments." (PMID 39795882, 2024). "We also depleted WRN in B16‐F10 melanoma cells by shRNA expressing lentiviral system or overexpressed WRN in COLO‐205 colon carcinoma cells, which are known have low WRN expression due to epigenetic silencing." (PMID 35582959, 2022). "From our list of prioritized variants and genes, three genes (MYO7A, WRN and NOP10) warrant a more detailed discussion, due to gene function and previous associations with melanoma." (PMID 35085295, 2022). "In both B16‐F10 melanoma and COLO205 colon carcinoma cells, WRN deficiency was strongly associated with enhanced sensitivity to nanomolar concentrations of CPT." (PMID 35582959, 2022). "A total of 9 patients (3.4%) carried mutations in high-to-moderate melanoma risk genes (CDKN2A, POT1, ACD) and 22 (8.3%) patients in other cancer syndrome genes (NBN, BRCA1/2, CHEK2, ATM, WRN, RB1)." (PMID 33050356, 2020). "In this regard, our results of animal studies revealed that CPT treatment (1 mg/kg body weight) significantly reduced WRN‐depleted melanoma, as compared to WRN‐proficient melanoma, indicating translational potential of TOP1 inhibitor therapy for cancer patients with WRN deficiency." (PMID 35582959, 2022). "In contrast, WRN and RECQL4 may have a tumor suppressor function in melanoma since melanoma has been reported in patients with loss of function mutations in these RecQ proteins." (PMID 25538733, 2014). "Here, our aim was to investigate whether patients in the Hungarian melanoma cohort (n = 17) with increased risk carry any pathogenic or likely pathogenic germline variants of the BRCA2, POLE, WRN, FANCI, PALB2, and RAD54B genes associated with melanoma survival and response to therapy." (PMID 39795882, 2024). "The top final variants and their corresponding genes most relevant to hereditary cancers and melanoma and present in both the patient and the sibling with a brain tumor, but not in the control, are in WRN, TYRP1, and ERCC2, shown in and discussed as follows." (PMID 38028607, 2023). "Although WRN and TYRP1 genes and their variations were correlated with different types of cancer, including melanoma, the currently identified WRN and TYRP1 variants were not reported previously in melanoma cases." (PMID 38028607, 2023).
cervical cancer (9 papers, 2012 to 2025). A primary or metastatic malignant neoplasm involving the cervix. "In line with this, the susceptibility of cervical cancer cells to irinotecan was likewise boosted by WRN DNA hypermethylation." (PMID 37092854, 2023). "Thus, in this study, the associations among cervical cancer, WRN expression, and cancer cell sensitivity to CPT-11 were investigated." (PMID 22797812, 2012). "For instance, in cervical cancer, methylation of the Casp8A2 gene is sufficient to increase drug resistance; on the contrary, hypermethylation of WRN confers cervical cancer cells high sensitivity to the topoisomerase I inhibitor (CPT-11)." (PMID 41195272, 2025). "For instance, cervical cancer cells were more sensitive to irinotecan after the downregulation of WRN." (PMID 37092854, 2023). "Treatment with a demethylating agent restored the WRN expression in cervical cancer cells and decreased their sensitivity to irinotecan." (PMID 37092854, 2023). "Decreased WRN mRNA expression negatively correlated with cervical cancer progression and WRN protein regulates the life cycle of viral carcinogen human papillomavirus 16 (HPV-16), linked with causing cervical and oropharyngeal cancers." (PMID 35782872, 2022). "Primary cervical cancer samples and cervical cancer cell lines were analyzed for WRN hypermethylation and found in 33.3% of patients and 33.3% of cancer cell lines." (PMID 35782872, 2022). "siRNA against WRN was transfected into a cervical cancer-derived cell line with high WRN expression." (PMID 22797812, 2012). "The sensitivity to CPT-11 of cervical cancer cells with aberrant methylation of WRN was decreased by treatment with a demethylating agent." (PMID 22797812, 2012). "Aberrant DNA hypermethylation and decreased expression of WRN were detected in 7/21 cases of primary cervical cancer and in two cervical cancer-derived cell lines." (PMID 22797812, 2012). "Aberrant methylation of the WRN gene in cervical cancer was examined using specimens collected for cytology." (PMID 22797812, 2012). "This study provided the first evidence of a relationship of WRN promoter methylation with cervical cancer, with aberrant methylation of WRN detected in 33.3% of specimens of cervical cancer and in two cervical cancer-derived cell lines." (PMID 22797812, 2012). "Aberrant DNA hypermethylation of WRN also increased the sensitivity of cervical cancer cells to CPT-11." (PMID 22797812, 2012). "In this study, we examined the relationship between aberrant DNA hypermethylation of WRN and the sensitivity of cervical cancer cells to anticancer drugs." (PMID 22797812, 2012). "Changes in WRN mRNA levels in cervical cancer-derived cell lines were analyzed before and after treatment with 5-aza, a demethylating agent." (PMID 22797812, 2012). "However, WRN and SIRT1 mRNA levels have an inverse relationship in CIN and cervical cancer; WRN levels reduce with increasing CIN grades while SIRT1 increases." (PMID 36230545, 2022). "Evaluation of WRN expression as a marker of sensitivity to CPT-11 may be clinically useful in treatment of cervical cancer." (PMID 22797812, 2012). "To assess if the small molecules identified by the in vitro WRN helicase activity screen using fluorometric and radiometric assays were biologically active in cell-based assays, we began by examining their effects on proliferation of the human cervical cancer cell line HeLa 1.2.11." (PMID 30625228, 2019). "In conclusion, our data suggest that aberrant methylation of WRN plays an important role in carcinogenesis and sensitivity to CPT-11 of cervical cancer." (PMID 22797812, 2012). "Among 6 cervical cancer-derived cell lines, aberrant methylation was detected in 2 cell lines, SKG-II and TCO-I, and mRNA and protein levels for WRN were lower in these cells." (PMID 22797812, 2012). "Selective downregulation of WRN expression using siRNA increased the sensitivity of cervical cancer cells to CPT-11, but not to other anticancer agents." (PMID 22797812, 2012).
cervical cancer (continued). "Thus, cervical cancers with BRIP1 and WRN alterations may be affected by PARP inhibitors." (PMID 36333792, 2022).
premature aging syndrome (9 papers, 2011 to 2022). Changes in the organism associated with senescence, occurring at an accelerated rate. "Premature aging syndromes that are associated with mutations in LMNA or WRN genes resemble normal aging in terms of gene expression." (PMID 34953016, 2022). "Deleterious mutations in this gene give rise to the premature aging syndrome Werner, and genetic variation in WRN has previously been associated with longevity." (PMID 26446717, 2016). "We show here for the first time that partial lipodystrophy with severe insulin resistance can reveal WRN-linked premature aging syndrome." (PMID 23849162, 2013). "WRN deficiency in WS patients leads to rare premature aging syndromes associated with an excess of unusual cancer types including soft tissue sarcomas, thyroid cancers, and meningiomas." (PMID 21267443, 2011). "In the context of premature-ageing syndromes, the absence of WRN (in WS) or the accumulation of progerin (in HGPS) also causes loss of heterochromatin and telomere attrition." (PMID 27482812, 2016).